VHL (von Hippel-Lindau tumor suppressor)
Diseases named in the same sentence as VHL in open-access papers (continued):
Sharing a sentence is not in itself a finding about the gene and the disease.
tumor (continued). "ccRCC is characterized by DNA alterations, including the copy number alterations (CNAs), as the loss of chromosome 3p and VHL inactivation, methylation and mutations, which are involved in tumor development and progression." (PMID 37370817, 2023). "VHL loss stabilizes hypoxia-induced factors (HIFs), which leads to activation of an array of tumor-growth-supporting pathways such as aerobic glycolysis, vasculogenesis, and cell survival." (PMID 36750850, 2023). "Cluster 1B tumours harbour pathogenic variants in genes involved in oxygen sensing (VHL, EPAS1, EGLN1/2)." (PMID 38124114, 2023). "First, genomic data showed that, next to VHL alterations (93.1%), most common driver gene mutations in ccRCC included alterations in tumor suppressor genes of different pathways such as SETD2 (90.3%) and PTEN (30.6%)." (PMID 37400554, 2023). "HIF-α-independent functions of VHL protein and their association with cellular processes involved in tumor development and progression." (PMID 36036061, 2023). "The massive sequencing, with a high level of readings, yielded three different mutated genes present at this tumour, in addition to the already known mutation in the inherited VHL gene." (PMID 37843608, 2023). "Overactivity of mTOR signaling is frequently observed in VHL-deficient ccRCC and related to an aggressive tumor phenotype and poor survival in ccRCC patients." (PMID 36831657, 2023). "Instead of acting in a manner dependent on the HIF-induced proangiogenic effect, FTO targets the glutamine transporter SLC1A5, modulating metabolic reprogramming and maintaining the survival of VHL-deficient tumour cells." (PMID 36859310, 2023). "Already in 2013, the genome of the clear cell RCC was identified, which is characterized by the absence or mutation of the VHL tumour suppressor gene (localized at 3p25) and frequent inactivation of the chromatin-modifying genes PBRM1, BAP1 and SETD2." (PMID 36672289, 2023). "Protein pVHL encoded by VHL gene functions as a tumor suppressor by acting as the substrate recognition component of the ubiquitin E3 ligase complex including Elongin B/C, Rbx1 and Cullin2." (PMID 36813923, 2023). "The causative role of Cyclin D1 in ccRCC tumor progression is highlighted by the fact that CCND1 knockdown in VHL deficient ccRCC cell lines attenuates xenograft growth in vivo." (PMID 36831657, 2023). "To investigate VHL and other oncogenic mutations of ccRCC, we established primary tumor cell lines and patient-derived xenografts (PDXs) in the chorioallantoic membrane (CAM) model from surgical specimens (cases #18-26)." (PMID 37069149, 2023). "Von Hippel–Lindau (VHL) is a tumor suppressor gene, and loss of its suppressor function is seen in heritable cancers linked with VHL syndrome as well as in some sporadic cancers." (PMID 36036061, 2023). "In particular, we explored the role of VHL, mTOR, chromatin modulators, DNA repair genes, cyclin-dependent kinases, and tumor mutation burden." (PMID 37887570, 2023). "Some genetic syndromes are associated with the development of other tumours, for example, VHL with renal, pancreatic and other tumours." (PMID 37761307, 2023). "Approximately 90% of ccRCCs harbour genetic alterations in von Hippel Lindau (VHL) tumour suppressor gene alleles." (PMID 36803783, 2023). "Mutational inactivation of the tumour suppressor VHL gene is an early genetic anomaly in the mainstream ccRCCs, leading to enhanced expression of the HIF-1α and HIF-2α transcription factors." (PMID 37174052, 2023). "These methods notably highlighted major tumor-stoma and tumor-immune interactions, interactions modulated when exposed to PD-1 blockade or upon VHL mutation, and molecules potentially driving tumor progression." (PMID 38025776, 2023). "A significant associations were found between allele G and genotypes AG and GG of rs779805 in the VHL tumor suppressor gene and increased tumor size, as well as high nuclear grade." (PMID 38115281, 2023).
tumor (continued). "For example, only 34% of all mutations detected by a multi-region sequencing approach were present in all regions of the tumor; of known ccRCC driver genes, only VHL was mutated ubiquitously." (PMID 37120552, 2023). "VHL mutations, for example, are associated with defined tumor margins, nodular tumor enhancement, and intratumoral vascularization, while a greater vein invasion is significantly associated with BAP1 mutations." (PMID 36902045, 2023). "For VHL, they described a mutation frequency of 53.2% and imaging characteristics of well-defined tumor margins, nodular tumor enhancement, and gross appearance of intratumoral vascularity." (PMID 36672304, 2023). "A significant associations were found between allele G and genotypes AG and GG of rs779805 in the VHL tumor suppressor gene and increased (>7 cm) tumor diameter." (PMID 38115281, 2023). "VHL deficiency can stabilize HIF2α function at tumor-specific gain enhancers thereby upregulating the expression of ccRCC-related oncogenes, such as ZNF395." (PMID 37190141, 2023). "The significance of Jade-1 as a tumor suppressor has previously been identified, particularly through its association with VHL." (PMID 37175531, 2023). "A tumor suppressor role of VHL has been validated based on association of VHL inactivation with a hereditary condition involving formation of tumors in multiple organs." (PMID 37850636, 2023). "In VHL-deficient RCCs, IL-6 production is increased, which propagates macrophage migration to the tumor site and polarization toward an M2-like phenotype." (PMID 37190141, 2023). "Loss of VHL is often associated with loss of other tumor suppressor genes including PBRM1, BAP1 and SETD2, which are also located on chromosome 3p." (PMID 37173966, 2023). "Further evidence of subclonal VHL copy number loss can be found by adjusting with only one of the computational measures of tumor purity (ABSOLUTE)." (PMID 37069149, 2023). "The VHL tumor suppressor has been implicated in the development of a dominantly inherited cancer syndrome known as VHL disease, as well as a number of sporadic cancers." (PMID 36036061, 2023). "VHL gene mutation caused the initial occurrence of the tumor, then real carcinoma progressed with the loss of large fragment in the chromosome 3p region." (PMID 37515929, 2023). "VHL loss causes the stabilization of HIF1/2α under normoxic conditions leading to increased expression of the tumor-promoting proteins normally expressed under hypoxic conditions." (PMID 37568390, 2023). "The L169P VHL variant was identified in the tumor of this aggressive case of ccRCC by whole-exome sequencing (WES), revealing a homozygous in-frame T506C transition that resulted in the L169P amino acid substitution." (PMID 37762376, 2023). "VHL is a tumour suppressor gene, and we postulate that the cause of the abnormal severity in the course of his disease, is an additional mutation in CHEK2, another tumour suppressor gene." (PMID 37843608, 2023). "Many of the metastatic phenotypes of our preclinical models were observed in clinical tumor specimens, including VHL loss resulting in the upregulation of HIF-1α and POSTN." (PMID 37069149, 2023). "A few of these tumors will pursue a linear evolution throughout their natural history, the so-called VHL-driven CCRCCs, but most will develop subsequent driver mutations, thus generating distinct clones within the tumor." (PMID 38136439, 2023). "Glucose deprivation or blocking the activity of GLUT-1 attenuates tumor formation and apoptosis of VHL-deficient RCC cells." (PMID 36831657, 2023). "Although mutation or inactivation of the Von Hippel-Lindau (VHL) tumor-suppressor gene is considered the hallmark of ccRCC, the second most mutated gene after VHL is PBRM1." (PMID 36674417, 2023). "In that study, we observed that all the cells with malignant features carried the VHL mutation in single cells’ analyses, thus were genetically proven tumor cells." (PMID 37444476, 2023).
tumor (continued). "These were commonly male patients with local tumours and mutations in VHL and wild-type FAT1 and STAG2." (PMID 37391505, 2023). "VHL is a tumor suppressor and is involved in the VHL-HIF pathway, its loss leading to an overexpression of HIF1 and HIF2, which also leads to VEGF overexpression triggering events such as proliferation, apoptosis and angiogenesis." (PMID 37228649, 2023). "In summary, our study shows that mRNA and protein levels of SCD5/fat-7 are substantially downregulated in VHL-deficient ccRCC tumor samples and ccRCC cells, as well as in C. elegans vhl-1 loss-of-function mutants." (PMID 36980176, 2023). "Another PPGL syndrome is caused by mutations in the tumour-suppressor gene VHL leading to Von Hippel–Lindau syndrome, which predisposes to a variety of malignant and benign tumours in various organs, including PC." (PMID 37761307, 2023). "The increased expression of c-Myc as well as its target genes in VHL-deficient ccRCCs, implies a pivotal role in tumor progression." (PMID 36831657, 2023). "Patient with missense VHL mutations harbour less tumours than those with nonsense mutations and deletions." (PMID 37843608, 2023). "VHL mutations have also been demonstrated in 46–82% of all sporadic cases of ccRCC, making it the most commonly altered oncogene in this type of tumor." (PMID 37887570, 2023). "The central pathway of tumor development in ccRCC is caused by the loss or inactivation of the tumor suppressor VHL located on chromosome 3p." (PMID 37173966, 2023). "Inclusion requirements were the presence of positive germline VHL variant test results and the presence of tumor testing, pathology results and somatic profile." (PMID 35774415, 2022). "In kidney cancer, it was shown that VHL mutations are significantly associated with well-defined tumor margins and nodular tumor enhancement." (PMID 35418998, 2022). "Occurring in approximately one in 35,000 live births, VHL disease is caused by a germline mutation and/or deletion in the VHL tumor suppressor gene, located on the short arm of chromosome 3." (PMID 36358730, 2022). "The increased expression of CPT1A specifically in VHL- cells treated to STF-62247 is quite intriguing since high expression of CPT1A limits tumor progression in VHL-mutated tumors." (PMID 35223522, 2022). "In progressively smaller subclones, genetic abnormalities are named ubiquitous (such as VHL loss and chromosome 3p loss, early, truncal events, in every tumor cell), shared, and private." (PMID 36358771, 2022). "In VHL-inactive ccRCC, histone lactylation is likely to act as a bridge between VHL deficiency and PDGFRβ hyperactivation to support tumor progression." (PMID 35637958, 2022). "Taken together, PGK1 upregulation is associated with VHL inhibition/mutation and tumor hypoxia in KIRC tissues." (PMID 35121728, 2022). "HIF2α deregulation plays an important role in VHL-defective tumours; however, HIF2α mutations have only been observed in some sporadic cases of PPGL and have not been observed in ccRCC6–8." (PMID 35760869, 2022). "Within the poorly differentiated component of the collision tumour, loss of heterozygosity in a VHL gene locus, and various chromosomal regions were identified." (PMID 35328664, 2022). "Clear cell RCC tumor cells almost universally display the loss of function of the von Hippel-Lindau (VHL) gene." (PMID 36180422, 2022). "VHL is an autosomal dominant inherited syndrome (1:36,000 births) whose patients are heterozygous for mutations in the VHL tumor suppressor gene (3p25–p26)." (PMID 35457036, 2022). "All VHL gene mutations in 20 ccRCC patients were different, indicating that each tumor was highly heterogeneous genetically." (PMID 35055428, 2022). "Mechanistically, FTO represses m6A modification of SLC1A5 mRNA and promotes its mRNA expression and translation, leading to increased glutamine uptake in RCC and enhanced tumor survival and progression, especially VHL-deficient cells." (PMID 36289851, 2022).
tumor (continued). "It appears that there is a distinction between erythrocytosis-causing VHL variations and VHL variations causing VHL disease with tumor development." (PMID 35205407, 2022). "As highlighted in this review, an improved understanding of VHL biology over the last several decades has paid large dividends for the treatment of both VHL disease-associated neoplasms and sporadic malignancies." (PMID 36358730, 2022). "Further supporting a hypoxic response to intrinsically promote T cell anti-tumor responses, T cells made genetically deficient in VHL or the PHD proteins that lead to proteolytic degradation of HIF-1α had increased anti-tumor activity." (PMID 35039633, 2022). "VHL controls matrix organization and its loss promotes a loosely organized and angiogenic matrix, predicted to be an early step in tumor formation." (PMID 36077607, 2022). "In renal clear cell carcinoma (ccRCC), loss of the von Hippel–Lindau (VHL) tumor suppressor causes upregulation of hypoxia signaling via HIF1 and HIF2." (PMID 36289851, 2022). "Mutations of VHL were significantly associated with well-defined tumor margins (p = 0.013), nodular tumor enhancement (p = 0.021), and gross appearance of intratumoral vascularity (p = 0.018)." (PMID 35055428, 2022). "Conversely, 104 out of 125 cells, defined as having uncertain malignant features according to pathological criteria, were, in fact, CTCs as they carried the identical VHL mutation also identified in the corresponding tumor tissue." (PMID 35207452, 2022). "In the rare tumoral disease of VHL, patients inherit a germline mutation in VHL, following an autosomal dominant pattern." (PMID 35163250, 2022). "Accordingly, in the RCC cohort, patients with a VHL mutation demonstrated a significant survival benefit compared to non-VHL-mutated patients, exceeding the predictive value of tumor mutational burden." (PMID 35798829, 2022). "We describe further evaluation with tumor tissue analysis as a complementary tool in the workup of such variant elusive VHL cases." (PMID 35304467, 2022). "Von Hippel-Lindau (VHL) is an important tumor suppressor, and its inactivation is a hallmark of inherited VHL disease and most sporadic clear cell renal cell carcinoma (ccRCC)." (PMID 35110537, 2022). "Another work identified increased expression of oncogenic pathways and mutations in known tumor suppressor genes such as VHL and TSC2 in tumor cells displaying HPD after therapy with anti-PD-1 therapy." (PMID 35922755, 2022). "In VHL-deficient and hypoxic ccRCC tumor cells, protein kinase growth arrest-specific 6 (GAS6)/AXL is activated by HIF1A and HIF2A." (PMID 35659268, 2022). "Of the 10,103 cells in the tumor sample, 5,395 (53%) had loss of chromosome 3p (encompassing the VHL locus) and formed a distinct cluster previously characterized as malignant cells by the authors based on marker gene expression." (PMID 36384128, 2022). "vHL results from a mutation in the VHL tumor suppressor gene which encodes the VHL protein, a regulator of angiogenesis." (PMID 36291833, 2022). "So, miRNA expression levels can distinguish VHL-associated tumors from sporadic ccRCC even though most differentially expressed miRNAs were similar between the two tumor groups." (PMID 36358771, 2022). "Upregulation and stabilization of HIFs is widely associated with angiogenesis, tumor progression, and immune evasion in various tumors, and HIFs are crucial for mediating the tumorigenic effects of mutated VHL, SDHx, and EGLN1 in PCC and PGL." (PMID 36699028, 2022). "Results revealed that all the cells diagnosed as CTC by the cytopathological analysis carried the VHL mutation detected in the corresponding tumor tissue." (PMID 35207452, 2022). "Bi-allelic inactivation of VHL or VHL promotor hyper-methylation and subsequent VHL transcriptional repression underlie two thirds of sporadic ccRCC cases, and VHL mutations occur at the earliest point of tumor formation." (PMID 35408930, 2022).
tumor (continued). "The H374R mutation is also associated with recurrent PGL, suggesting a crucial role for PHD2/EGLN1 as a tumor suppressor gene that is similar to VHL missense mutations seen in type 2 VHL disease, i.e., high risk of PCC/PGL." (PMID 36699028, 2022). "One study with renal tumors showed that 104 of 125 CTCs identified by cytopathological analysis expressed the identical VHL mutation as detected in the primary tumor." (PMID 36499015, 2022). "In the multivariable-adjusted results (model 2) that included patient clinical characteristics (tumour grade, size and stage), the association became stronger [HR (95% CI), VHL = 0.33 (0.14–0.79), PBRM1 = 0.25 (0.08–0.79)]." (PMID 35444164, 2022). "Each simulation starts from a single tumour voxel carrying VHL and 3p loss and ends when the size exceeds 1 million tumour voxels, reflecting a tumour diameter of approximately 12 cm." (PMID 34949820, 2022). "Von Hippel–Lindau disease is an autosomal dominantly inherited tumor predisposition syndrome with germline mutations in a tumor suppressor gene on chromosome 3 (VHL gene 3p25.3)." (PMID 35546652, 2022). "The mean time from TCE exposure onset to detection of a tumor with a VHL gene TCE-linked hotspot mutation was 23 years." (PMID 35055441, 2022). "Von Hippel Lindau disease, an autosomal dominant condition caused by a mutation in the VHL tumour-suppressor gene, is the most common type of hereditary renal cell carcinoma." (PMID 35328664, 2022). "Sporadic tumours were shown to carry germline mutation in the VHL gene in 39% of cases and 32% of VHL patients initially presented with ELST." (PMID 35397067, 2022). "Tumor profile demonstrated somatic biallelic alterations of VHL (i.e., inactivating somatic SNV in one allele and a one copy deletion in the other allele), consistent with somatic LOH." (PMID 35774415, 2022). "Most prominently, mutations in the tumour suppressor von Hippel–Lindau (VHL), which inhibits the transcription factor hypoxia-inducible factor (HIF), occur in kidney cancers, and the resulting accumulation of HIF drives tumour growth." (PMID 35285794, 2022). "The expression level of FDX1 in ccRCC samples with different ages, gender, pathological tumor stage, histological tumor grade, VHL mutation, and PBRM1 mutation was analyzed." (PMID 36292610, 2022). "Given all selected cases are positive for a germline VHL variant, careful examination of the tumor signature profile of the VHL gene and genomic regions affecting the VHL gene is imperative." (PMID 35774415, 2022). "The von Hippel–Lindau (VHL) disease is an autosomal dominant cancer syndrome caused by mutations in the VHL tumor suppressor gene." (PMID 35388293, 2022). "A transcriptomic analysis of 76 inherited and sporadic PPGLs identified 2 tumour clusters, one including SDHB, SDHD and VHL-mutated tumours (pseudohypoxic signalling cluster), and one comprising RET and NF1-mutated (kinase signalling cluster) tumours." (PMID 35938916, 2022). "This tumor type is associated with a high prevalence of VHL mutation and constitutive activation of HIF." (PMID 36384128, 2022). "VHL disease’s incidence ranges from 1/36,000 to 1/45,000 live births and is caused by mutations in the VHL tumor suppressor gene, which is located in the short arm of chromosome 3 (3p25-26)." (PMID 35388293, 2022). "That is, VHL mutation acts as an initiative event to induce tumor occurrence, while PBRM1, BAP1 and SETD2 cause DNA repair defect and cell overgrowth." (PMID 35918352, 2022). "Approximately 90% of ccRCCs harbor an inactivation of both von Hippel Lindau (VHL) and tumor-suppressor gene alleles." (PMID 35955582, 2022). "Von Hippel-Lindau (VHL) disease tumour suppressor gene VHL was found mutated in a unique case of clear cell epithelioid PM in a non-exposed women." (PMID 35223506, 2022).